ENSG00000295084 (novel transcript, antisense to KCNH7)
Gene: Long non-coding RNA gene on chromosome 2 (162,490,274 to 162,497,127, forward strand). Ensembl gene ENSG00000295084.
Gene Ontology:
Molecular function: structural constituent of ribosome
Cellular component: ribosome